ENG (endoglin)
Diseases named in the same sentence as ENG in open-access papers (continued):
Sharing a sentence is not in itself a finding about the gene and the disease.
chondrosarcoma (2 papers, 2012 to 2013). A malignant cartilaginous matrix-producing mesenchymal neoplasm arising from the bone and soft tissue. "An association between angiogenesis and endoglin expression could only be approached in vitro in chondrosarcoma cells and animal models." (PMID 23088614, 2012). "From the 10 chondrosarcoma samples with high endoglin expression, 9 showed endoglin expression in more than 50% of tumor cells." (PMID 23088614, 2012). "Immunohistochemical analysis furthermore revealed that phosphorylated Smad1/5/8 and endoglin expression were significantly higher in high-grade compared to low-grade chondrosarcoma and correlated to each other." (PMID 23088614, 2012). "Only one grade I chondrosarcoma showed a sum score for endoglin higher than 3 and high endoglin expression was significantly more frequent in high-grade tumors." (PMID 23088614, 2012). "In central chondrosarcoma, we found significantly higher expression of endoglin in high-grade tumors and a correlation of endoglin expression to Smad1/5/8 activity." (PMID 23088614, 2012). "This correlation suggests that endoglin expression in high-grade chondrosarcoma could represent a determinant of elevated Smad1/5/8 activation in these tumors." (PMID 23088614, 2012). "In this context, thus, endoglin and Smad1 signaling correlate to undifferentiated states of proliferating chondrogenic precursors, which is in line with higher expression levels in high-grade chondrosarcoma." (PMID 23088614, 2012). "In order to establish whether endoglin could influence TGFβ signaling in chondrosarcoma, we have assessed its expression in chondrosarcoma by immunohistochemical analysis." (PMID 23088614, 2012). "The correlation of Smad1/5/8 activity to endoglin expression suggests that, as described in other cell types, endoglin could enhance Smad1/5/8 signaling in high-grade chondrosarcoma cells." (PMID 23088614, 2012). "This correlation suggests that, as described in other cell types, endoglin could enhance Smad1/5/8 signaling in high-grade chondrosarcoma cells." (PMID 23088614, 2012). "Endoglin expression coupled to Smad1/5/8 activation could thus represent a functionally important signaling axis for the progression of chondrosarcoma and a regulator of the undifferentiated phenotype of high-grade tumor cells." (PMID 23088614, 2012). "We have shown that the BMP and TGFβ signaling pathways are active in conventional central chondrosarcoma and that phosphorylated Smad1/5/8 and endoglin expression were significantly higher in high-grade compared to low-grade chondrosarcoma and correlated to each other." (PMID 23088614, 2012). "The dissection of signaling pathways in chondrosarcoma cells would be necessary to determine whether the correlation of endoglin expression to Smad1/5/8 phosphorylation in these cells truly reflects an enhanced activation of this signaling axis in high grade chondrosarcoma." (PMID 23088614, 2012). "Therefore, the hypothesis can be made that endoglin could represent an important mediator of tumor angiogenesis in high-grade chondrosarcoma." (PMID 23088614, 2012).
colitis (2 papers, 2014 to 2022). Inflammation of the colon. "Endoglin haploinsufficiency may affect susceptibility to infection, and therefore, we assessed the relative abundance of various gut bacterial groups at days 18–23 of colitis." (PMID 25114380, 2014).
coronary atherosclerosis (2 papers, 2015 to 2021). Atherosclerosis of the coronary vasculature. "Interference with endoglin can alter the course of coronary atherosclerosis." (PMID 34602076, 2021). "Given the importance of endoglin in the progression of coronary atherosclerosis, its immunological properties in the course of the disease provide an excellent entry point for studying the immunological mechanisms of coronary atherosclerosis." (PMID 34602076, 2021). "In this study, bioinformatics analysis revealed changes in endoglin and TGF-ß in the course of blood lipid-mediated coronary atherosclerosis." (PMID 34602076, 2021). "The aim of this study was to evaluate associations of the serum level of these factors and of the related angiogenesis inhibitor, endoglin (ENG), with burden of coronary atherosclerosis." (PMID 26213574, 2015).
cystic fibrosis (2 papers, 2013 to 2019). Autosomal recessive disorder caused by pathogenic variants in the CFTR gene (cystic fibrosis transmembrane conductance regulator), which encodes a chloride and bicarbonate channel expressed in epithelial cells, and follow the diagnosis criteria. "Endoglin (ENG) regulates signaling by transforming growth factor‐β (TGF‐β), a genetic modifier of cystic fibrosis lung disease severity." (PMID 30806029, 2019).
dyslipidemia (2 papers, 2020 to 2022). "Relative expression of miR-34a and serum endoglin and ICAM concentrations were higher in patients than controls (p=0.001) and in patients with dyslipidemia (42 patients) compared to patients without dyslipidemia (78 patients) (p=0.01)." (PMID 32654473, 2020). "Levels of serum endoglin and serum ICAM were significantly higher in patients with T1DM than healthy subjects (p=0.01 and p=0.001, respectively) and higher in T1DM patients with dyslipidemia compared to patients without dyslipidemia (p=0.01)." (PMID 32654473, 2020).
endometrioid ovarian cancer (2 papers, 2015). "In particular, miR-208a repressed endoglin expression in the heart, whereas miR-370 was negatively correlated with endoglin expression in endometrioid ovarian cancer cells." (PMID 26228095, 2015). "As a consequence, endoglin over-expression contributes to the enhanced malignant properties in endometrioid ovarian cancer cells including high proliferation, low apoptosis and/or cell death, and enhanced chemoresistance." (PMID 27047316, 2015). "Taken together these investigators hypothesized that, in endometrioid ovarian cancer cells, hypermethylation reduces miR-370 levels which in turn results in the elevated expression of its direct target endoglin." (PMID 27047316, 2015).
fibrosarcoma (2 papers, 2020 to 2026). A malignant mesenchymal fibroblastic neoplasm affecting the soft tissue and bone. "Indeed, while we previously found that fibronectin was a critical exosome cargo driving nascent adhesion formation, lamellipodia stabilization, and cell speed in HT1080 fibrosarcoma cells, fibronectin was unable to rescue the filopodia defect of endoglin-KD HT1080 cells in this study." (PMID 41532547, 2026). "Finally, we assessed the role of endoglin in filopodia formation in HT1080 fibrosarcoma cells." (PMID 41532547, 2026).
haemorrhagic stroke (2 papers, 2008 to 2022). "Three studies (285 cases; 512 controls) investigated risk of haemorrhagic stroke and the exon 7/8 GA insertion of the gene encoding endoglin." (PMID 19008959, 2008).
head and neck carcinoma (2 papers, 2019 to 2020). A carcinoma that arises from the head and neck region. "This suggests endoglin could be an important marker of late radiation toxicity in head and neck cancer patients as well." (PMID 31500214, 2019).
hematoma (2 papers, 2019 to 2023). A hematoma is a collection of blood from a vascular structure into an extravascular space. "ANG-2, EGF, Endoglin, and CXCL4 expression were higher in HUVECs treated with hematoma-derived exosomes (EX-Hematoma group) compared to those treated with serum-derived exosomes (EX-Serum group)." (PMID 31841443, 2019). "Endoglin expression was minimally detected in the aortic tunica media from pigs that received 4 weeks HFD as well as control healthy pig aorta not subjected to hematoma injection and HFD." (PMID 37063951, 2023).
hepatoblastoma (2 papers, 2021). Hepatoblastoma (HB) is a malignant hepatic tumor and is the most common pediatric liver cancer. "In a model of HepG2 hepatoblastoma-bearing nude mice, microbubbles conjugated with anti-mouse anti-endoglin antibodies had a significantly higher dTE than microbubbles conjugated with an isotype IgG in the vasculature of the xenografted tumor." (PMID 33946583, 2021).
hyperlipidaemia (2 papers, 2010 to 2021). "On the other hand, in the hyperlipidaemia mouse model, soluble endoglin was significantly downregulated by statin therapy, but its expression on the aorta was significantly increased." (PMID 34602076, 2021).
kidney cancer (2 papers, 2020 to 2021). Primary or metastatic malignant neoplasm involving the kidney. "Furthermore, endoglin was shown to be essential for EMT in kidney cancer cells as reduction of endoglin levels by shRNA increased epithelial markers and reduced mesenchymal markers." (PMID 32150964, 2020).
left ventricular hypertrophy (2 papers, 2010 to 2020). Enlargement of the LEFT VENTRICLE of the heart. "There are significant correlations between endoglin and glycemia, systolic blood pressure, pulse pressure, pressure wave velocity and electrocardiographically assessed left ventricular hypertrophy." (PMID 21171985, 2010).
leprosy (2 papers, 2013 to 2016). Leprosy is a chronic infectious disease affecting primarily the skin and peripheral nervous system. "The aim of this study was to evaluate angiogenesis and lymphangiogenesis across the spectrum of leprosy, in its reactional episodes and in its residual lesions by immunohistochemistry (IHC), using the markers CD31, CD105/endoglin and D2-40/podoplanin." (PMID 24040306, 2013).
lung disease (2 papers, 2013 to 2019). "Quantitative PCR, immunoblotting of lung homogenate, ENG immunohistochemistry, and ELISA of BAL fluid all demonstrate increased endoglin in CF pulmonary disease." (PMID 30806029, 2019). "Marked Elevations of endoglin in end‐stage CF lung specimens underscores the importance of endoglin to tissue fibrosis, and suggests a contribution of endoglin to CF lung disease progression." (PMID 30806029, 2019).
mammary adenocarcinoma (2 papers, 2013 to 2015). "In vivo, silencing of endoglin with triple electrotransfer of siRNA molecules into TS/A mammary adenocarcinoma also significantly reduced the mRNA levels, number of tumor blood vessels and the growth of tumors." (PMID 23593103, 2013). "Finally, the therapeutic potential of siRNA molecules against endoglin was investigated in vivo in BALB/c mice bearing TS/A mammary adenocarcinoma." (PMID 23593103, 2013). "The murine mammary adenocarcinoma TS/A, growing in immunocompetent BALB/c mice, was used in vivo as tumor model where tumor cells do not express endoglin or ET, and therefore the effect of GET of plasmids silencing endoglin should be based on vascular targeted effects." (PMID 25909447, 2015). "In addition, we demonstrated that the transfection of siRNA molecules targeting murine endoglin does not reduce the proliferation of murine mammary adenocarcinoma cells TS/A, which express very low levels of endoglin mRNA." (PMID 23593103, 2013).
ovarian tumors (2 papers, 2019 to 2026). "Indeed, recurrent ovarian tumors are enriched in CSCs that express high levels of GLI2 and components of TGF-β pathway, such as the co-receptor endoglin (CD105)." (PMID 31244888, 2019).
pancreatic adenocarcinoma (2 papers, 2021 to 2024). "Comparably, dual targeting of human pancreatic adenocarcinomas (BXPC-3 cell line) in an orthotopic mouse model was achieved with a 64Cu-NOTA-conjugated heterodimer of anti-tissue factor and anti-endoglin Fab." (PMID 33946583, 2021).
pancreatitis (2 papers, 2015 to 2021). Inflammation of the pancreas. "Endoglin expression of vascular endothelial cells in pancreatitis is unknown." (PMID 34885196, 2021). "The applicability of targeting endoglin for molecular imaging of PDAC has to be demonstrated, since exact expression profiles of endoglin on PDAC precursor lesions as well as pancreatitis is not specifically studied, which could hamper its diagnostic value." (PMID 34885196, 2021).
peripheral vascular disease (2 papers, 2011 to 2023). Any disorder affecting blood flow through the veins or arteries outside of the heart. "We found that APOE, IGF1R, HMGCR, APOA1, ENG, SERPINA3 and LCN2 were hub proteins in the network, which were also predicted to be associated with peripheral vascular disease." (PMID 37496672, 2023).
peritonitis (2 papers, 2016 to 2019). Inflammation of the peritoneum (tissue that lines the abdominal wall and covers most of the organs in the abdomen). "Thus, MΦ endoglin knockout mice show a predisposition to develop spontaneous infections by opportunistic bacteria, increased survival following LPS-induced peritonitis, and impaired phagocytic activity in endoglin deficient peritoneal MΦ." (PMID 31242676, 2019). "Peritonitis was induced by injecting Zymosan A in the peritoneal cavity, the so called Zymosan induced peritonitis or ZIP model in order to investigate endoglin expression in MΦ derived from peripheral blood Mo and recruited to the PerC." (PMID 27010826, 2016).
pituitary tumor (2 papers, 2019 to 2022). A benign or malignant neoplasm affecting the pituitary gland. "Expression of endothelial markers CD31, CD34, and ENG was significantly higher in pituitary tumors, by 5.6, 22.3, and 8.2-fold, respectively, compared to in normal pituitary tissue." (PMID 35600354, 2022). "Compared with normal pituitary tissue, RNA levels of CD31, CD34, and ENG were increased in pituitary tumors by 5.6 (p<0.0001), 22.6 (p<0.0001), and 8.2 (p<0.0001) fold, respectively." (PMID 35600354, 2022). "Because mRNA levels may not truly reflect their respective protein levels, we measured protein levels of CD31, CD34, and ENG in 12 additional pituitary tumors using ELISA assays." (PMID 35600354, 2022). "The RNA transcripts detected in pituitary tumors for CD31, CD34 and ENG were 1.6 x 104, 3.3 x 104, and 1.0 x 105 copies/μg total RNA, respectively." (PMID 35600354, 2022).
placental insufficiency (2 papers, 2016 to 2022). Failure of the placenta to deliver an adequate supply of nutrients and oxygen to the fetus. "The suggested pathogenic mechanisms of ENG, LEP, and FLT1 related to placental insufficiency IUGR needs further validation in cell and/or animal model." (PMID 35090410, 2022). "The key genes LEP and ENG have potential to serve as circulating diagnosis biomarkers and therapeutic targets for placental insufficiency IUGR." (PMID 35090410, 2022). "A holistic gene expression profile of placental insufficiency IUGR has been generated and the key genes ENG and LEP has potential to serve as circulating diagnosis biomarkers and therapeutic targets for placental insufficiency IUGR." (PMID 35090410, 2022). "The expression of genes ENG, LEP, and FLT1 were significantly upregulated in placental insufficiency IUGR." (PMID 35090410, 2022). "ENG, LEP, and FLT1 were identified as key genes related to placental insufficiency IUGR, Significantly higher expression of ENG and LEP at RNA level in this disease was validated reliable by three GEO datasets repeatedly." (PMID 35090410, 2022). "Thus, overexpression of ENG (p = 0.03) and LEP (p = 0.03) was significantly related to placental insufficiency IUGR status." (PMID 35090410, 2022). "Thus, ENG and LEP as biomarkers were detected and validated in the placental tissue from pregnancies complicated by placental insufficiency IUGR." (PMID 35090410, 2022). "This study identified and validated ENG and LEP as key genes in the placental tissue from pregnancies complicated by placental insufficiency IUGR, with the clinical signs of asymmetric growth, oligohydroamnions, and/or increased pulsatility index of the umbilical artery." (PMID 35090410, 2022).
renal dysfunction (2 papers, 2010 to 2011). "In this study, we analyzed 216 individuals with various degrees of renal dysfunction and were unable to confirm an association between CKD and increases in the concentration of soluble endoglin." (PMID 21886815, 2011). "We found, in fact, that patients with ESRD, the most severe form of renal dysfunction, had on average the lowest circulating concentration of soluble of endoglin." (PMID 21886815, 2011).
Shock (2 papers, 2022 to 2023). The state in which profound and widespread reduction of effective tissue perfusion leads first to reversible, and then if prolonged, to irreversible cellular injury. "In a clinical study of patients with septic shock, circulating endoglin levels were significantly higher in patients with early mortality in septic shock." (PMID 37700349, 2023). "Soluble endoglin, which is released in the increased quantities from endothelial cells during hypoxia and oxidative stress (i.e., factors strongly expressed in septic shock) has been considered by some authors as a marker of the degree of endothelial activation and dysfunction." (PMID 36117974, 2022).
teratoma (2 papers, 2021 to 2024). A non-seminomatous germ cell tumor characterized by the presence of various tissues which correspond to the different germinal layers (endoderm, mesoderm, and ectoderm). "Initially, they demonstrated via autoradiography that 59Fe-radiolabeled αCD105-PAA-SPIONs could accumulate at endoglin-expressing, highly vascularized teratocarcinomas in mice (F9 teratoma model)." (PMID 33946583, 2021).
urothelial carcinoma (2 papers, 2018 to 2022). A malignant neoplasm derived from the transitional epithelium of the urinary tract (urinary bladder, ureter, urethra, or renal pelvis). "Recently, a chimeric monoclonal antibody (TRC105) targeting ENG has entered clinical trial to treat patients with advanced urothelial carcinoma, indicating that ENG may be a promising anti-angiogenic target of cancer therapy." (PMID 29484142, 2018).
vascular occlusion (2 papers, 2016 to 2018). "Increased generation of endoglin+ EMPs in CTEPH is likely to represent a protective mechanism supporting endothelial cell survival and angiogenesis, set to counteract the effects of vascular occlusion and endothelial damage." (PMID 26786759, 2016).
viral infection (2 papers, 2022 to 2023). "The endothelial genes PECAM1/CD31 and ENG were both enriched in regions of viral infection, further supporting our assertion of viral infection at the capillary bed." (PMID 36968839, 2023). "Levels of soluble endoglin (sENG) were also slightly elevated 48 h after infection for both viruses, perhaps because of the activation induced by viral infection, as previously observed with dengue virus." (PMID 35337059, 2022).
AIDS (1 paper, 2015). A syndrome resulting from the acquired deficiency of cellular immunity caused by the human immunodeficiency virus (HIV). "In AIDS KS patients, endoglin stains were positive in the endothelium of tumour associated vessels of most KS biopsies." (PMID 26296972, 2015). "We could, therefore, speculate that plasma endoglin concentration of AIDS KS patients may result from an increased endoglin cleavage from membrane endoglin of the tumour cells and decreased membrane localization." (PMID 26296972, 2015).
aneurysm (1 paper, 2016). Bulging or ballooning in an area of an artery secondary to arterial wall weakening. "Whether the differences in TGFβ and endoglin levels in BAV patients are some of the causes of aneurysm development in BAV is unclear." (PMID 27110824, 2016). "Endoglin regulates the expression and activation of endothelial nitric oxide synthase, which is believed to play a role in angiogenesis and in the composition of vascular resistance in aneurysm formation." (PMID 27110824, 2016).
aortic aneurysm (1 paper, 2021). A ruptured aneurysm located in the wall of the proximal portion of the descending aorta proceeding from the arch of the aorta. "Endoglin/CD105 has a high sensitivity for the detection of microvessels in atherosclerotic plaques, is involved in the pathophysiology of atherosclerotic lesions, is upregulated in aortic aneurysms, and contributes to shear-induced collateral artery growth." (PMID 33946583, 2021).